DLK1 (delta like non-canonical Notch ligand 1)
Diseases named in the same sentence as DLK1 in open-access papers (continued):
Sharing a sentence is not in itself a finding about the gene and the disease.
cancer (continued). "Similar to IGF2 and H19, DLK1 and MEG3 also perform diverse biological functions in cancers." (PMID 38812777, 2024). "This suggests that, in addition to their effect on SNAI2 and CDH gene expression, both DLK1 and DLK2 may affect other shared mechanisms that modulate the invasive properties of MDA-MB-231 and other cancer cells." (PMID 35163478, 2022). "Additionally, upregulated genes included H19, IGF2 and DLK1, all regulated by PLAGL1 and with known functions in tumorigenesis of different cancers." (PMID 34355256, 2021). "In conclusion, the Dlk1-Dio3 repression in Snail-expressing lung tumors seems to be mediated by a soluble factor secreted from Snail-expressing cancer cells, which does not reside in exosomes." (PMID 30190790, 2018). "In conclusion, these results point towards a non-cell autonomous regulation of the Dlk1-Dio3 locus in immune cells by a soluble factor secreted by Snail expressing cancer cells that does not reside in exosomes." (PMID 30190790, 2018). "Herein, we have demonstrated that Snail-expressing cancer cells release a soluble factor that does not reside in exosomes and is capable of downregulating the Dlk1-Dio3 locus in immune cells." (PMID 30190790, 2018). "In summary, a series of DNA methylation surveys revealed that a relatively large fraction of imprinted genes are epigenetically affected in human cancers, and also that this epigenetic instability is particularly pronounced in a subset of imprinted genes, such as PEG3, IGF2, DLK1, MEST and GNAS." (PMID 26338779, 2015). "The nonclassical ligand DLK1 was found to be aberrantly expressed in several human cancers, including neuroblastoma, hepatocellular carcinoma, gliomas and human prostate cancer." (PMID 24621612, 2014). "Of note, plasma membrane NOTCH1 was uniquely associated with the ablumenal aspect of the endothelium, in direct contact with closely adherent perivascular cells that expressed the HIF-induced non-canonical NOTCH antagonist DLK1, a cancer pericyte-related antigen, together with SMA and PDGFRA." (PMID 29305721, 2018). "Interestingly, we also observed that DLK1 could still moderately upregulate MMP9 expression when the Notch signaling pathway was blocked, implying that DLK1 may function in cancer invasion in both Notch signaling-dependent and -independent manners." (PMID 24621612, 2014). "Indeed, an overlay of nucleosome prediction at all analyzed regulatory regions (DLK1 promoter, MEG3 and IG DMR) with our experimentally obtained methylation patterns suggest strongly positioned and potentially newly phased nucleosomes in cancer compared to benign urothelial cells." (PMID 25741387, 2014). "Although not covered in the current investigation, cancer stem cell markers including CD133, CD44, DLK1, and Notch1 as well as the β-catenin/p-GSK3β signaling pathway were significantly down-regulated, and the self-renewal capacity of CSCs was suppressed." (PMID 39000345, 2024). "In several previous reports on other cancer types, either MEG3 or DLK1 was reported to become deregulated, but not both." (PMID 29348851, 2017). "Due to the heterogeneous expression of DLK1 in ACC17, we next assessed for potential bystander killing by which hydrophobic payloads such as PBD can diffuse from target antigen-expressing cancer cells after direct ADC cytotoxicity into neighboring antigen-negative cancer cells." (PMID 40595495, 2025).
metabolic disease (9 papers, 2018 to 2024). A congenital disorder (due to inherited enzyme abnormality) or acquired (due to failure of a metabolically important organ) disorder resulting from an abnormal metabolic process. "Previous studies have shown that imprinted gene expression at the Dlk1/Dio3 domain is important for fetal growth, the timing of human puberty, and susceptibility to metabolic disease." (PMID 30182198, 2018). "Therefore, disruption of DLK1 dosage has important consequences for energy homeostasis and metabolic disease." (PMID 37589451, 2023). "Based on this study, it may be considered that DLK1 could be culpable for metabolic disorders in GDM." (PMID 34540403, 2021). "However, in the ART-associated phenotype the increased risk for LBW, SGA, rapid postnatal growth, and metabolic disorders would be a consequence of downregulation of DLK1 caused by subfertility associated disorder, not a consequence of poor maternal nutrition as in the example of fetal programming." (PMID 39702541, 2024).
infection (5 papers, 2018 to 2023). The state of being infected such as from the introduction of a foreign agent such as serum, vaccine, antigenic substance or organism. "This expression pattern was reversed at 150 dpi (the latest stage of infection), when the downregulation of DLK1 occurred (150 dpi)." (PMID 34804009, 2021). "As we show herein, cells expressing DLK1 decreases in density in the spleen over the course of infection." (PMID 34804009, 2021). "Along the course of the present experimental infection model, we observed a progressive decrease in DLK1 expression, with WP disruption taking place by 150 dpi." (PMID 34804009, 2021). "Downregulation of DLK1 was reported in mice infected with L. donovani at 21 and 42 days of infection." (PMID 34804009, 2021). "We propose that the histological changes seen during the course of infection correlated with the transcriptional differential gene expression and tissue distribution of T lymphocyte marker and DLK1 protein." (PMID 34804009, 2021). "Following infection, at 30 dpi, DLK1 was found to be significantly differentially expressed concomitant with the histological detection of lymphoid hyperplasia." (PMID 34804009, 2021).
cardiovascular disease (3 papers, 2018 to 2024). "We have previously shown that increased DLK1 amounts associates with increased pericardial fat, a key risk for cardiovascular disease." (PMID 38328889, 2024). "Although the physiological contributions of these circulating Dlk1-Dio3 locus miRNAs remain unclear, their dynamic expression may have utility as a panel of biomarkers for cardiovascular disease." (PMID 29996488, 2018). "In other cardiovascular diseases, reduced levels of Dlk1-Dio3 miRNAs have been reported." (PMID 29996488, 2018). "Taken together, the Dlk1-Dio3 locus represents a largely unexplored noncoding regulator of cardiac homeostasis, harboring numerous ncRNAs that may serve as therapeutic targets for cardiovascular disease." (PMID 29996488, 2018). "Once Dlk1-Dio3 noncoding RNAs are understood for their dynamic roles in cardiomyocyte differentiation, proliferation and hypertrophy, this knowledge can inform medical applications aimed at improved diagnostics, therapeutics, and regenerative strategies for treatment of cardiovascular disease." (PMID 29996488, 2018).
cardiac disease (2 papers, 2018 to 2024). "Future studies addressing patient specific variations of DLK1 and its association to heart disease may be valuable, as is the testing of site‐specific inhibition of DLK1 in the pericardial compartment to avoid potential adverse events systemically." (PMID 38328889, 2024). "We first explore a large body of findings that implicate many Dlk1-Dio3 miRNAs in cardiomyocyte proliferation and differentiation, heart development, and cardiac disease pathways." (PMID 29996488, 2018).
hematologic malignancies (2 papers, 2021 to 2025). "Our results suggest an important role for deregulation of the DLK1 gene in BM niche remodeling and disease progression in context of hematologic malignancies." (PMID 33723276, 2021).
kidney disease (2 papers, 2022 to 2023). "Whereas CTSH and DLK1 have not been associated with kidney disease, studies have shown increased TYRO3 mRNA expression and increased circulating and urinary TYRO3 levels in patients with DKD, further supporting a causal role." (PMID 36349687, 2023).
myopathies (2 papers, 2013 to 2022). "In a recent study, we demonstrated that Dlk1 is expressed in rodent muscle during regeneration, in human fetal muscle and in myopathies, with localization to both satellite cells and myotubes." (PMID 23577150, 2013).
neurodegenerative disease (1 paper, 2017). A disorder of the central nervous system characterized by gradual and progressive loss of neural tissue and neurologic function. "The specificity of the MIG-15/JNK-1 pathway compared to the DLK-1/PMK-3 and MLK-1/KGB-1 pathways in worms suggests inhibitors of specific JNK isoforms could have differing efficacy in neurodegenerative disease models." (PMID 29228003, 2017).
neurodevelopmental disorder (1 paper, 2013). A behavioral and cognitive disorder with onset during the developmental period that involves impaired or aberrant development of intellectual, motor, or social functions. "The Snrpn-Ube3a and Dlk1-Dio3 regions have also been associated with several neurodevelopmental disorders." (PMID 23580197, 2013). "Furthermore, ∼20% of the altered ncRNAs mapped to three imprinted regions (Snrpn-Ube3a, Dlk1-Dio3 and Sfmbt2) that showed differential methylation and have been previously implicated in neurodevelopmental disorders." (PMID 23580197, 2013).
DLK1 also shares sentences with these, for which no sentence is quoted: metabolic syndrome (5 papers); Autoimmunity (4); phaeochromocytoma (4); adrenal tumors (3); Nephroblastoma (3); small cell lung carcinoma (3); cervical cancer (2); endothelial dysfunction (2); germ cell tumor (2); giant cell tumor of bone (2); lipodystrophy (2); pancreatic cancer (2); paraganglioma (2); pheochromocytoma (2); thyroid cancer (2); Uterine leiomyoma (2); adrenal cancers (1); adrenocortical tumors (1); alveolar rhabdomyosarcoma (1); angiosarcoma (1); anorexia nervosa (1); asthma (1); autism spectrum disorder (1); Cachexia (1); childhood tumors (1); Chronic Obstructive Asthma (1); cognitive decline (1); colon adenocarcinoma (1); coronary artery disease (1); dementia (1).
A further 37 diseases each share a sentence with DLK1 in 1 paper.